NRXN3 (neurexin 3)
Diseases named in the same sentence as NRXN3 in open-access papers (continued):
Sharing a sentence is not in itself a finding about the gene and the disease.
tumor (10 papers, 2013 to 2025). "The MBEN tumor microanatomy is visible in the H&E staining, and its structure was highlighted by all iST methods at the transcript level, with the transcription of NRXN3 and LAMA2 as marker genes for the nodular and internodular compartments, respectively." (PMID 40542418, 2025). "Among all 169 potential cancer drivers, 33 genes, including Notch1, Jup and Met, showed oncogenic features, whereas the majority of genes, including Lipc, Cntn5, Hdac4, Nrxn3 and Cntnap5c, exhibited tumour suppressor features." (PMID 32591500, 2020). "However, the Visium analysis did not offer sufficient spatial resolution to distinctly delineate the two tumor compartments, as indicated by the NRXN3/LAMA2 expression ratio." (PMID 40542418, 2025). "Furthermore, we observed for NRXN3 mRNA expression, we found that NRXN3 mRNA was down-regulated in tumor cells than the paired adjacent normal brain tissues." (PMID 23383267, 2013). "While all three variants confirmed by SP-ddPCR (i.e., LAMC3 c.1241G>A, NRXN3 c.308G>A, and ASNA1 c.193C>T) were present in the surrounding colon mucosa, they were absent in the matched cancerous tissues, advocating a negative selection during tumor evolution." (PMID 37923774, 2023).
cancer (9 papers, 2013 to 2025). A tumor composed of atypical neoplastic, often pleomorphic cells that invade other tissues. "We could detect mutations on NRXN1 and NRXN3 in 950 cancer samples across 32 cancer types." (PMID 35052689, 2021). "In contrast, a distinct set of female-amplified genes, such as NRXN3 and EFNB2, are linked to the same pathway in comparable cancer types." (PMID 39716176, 2024). "NRXN3, a member of the neurexin gene family, is involved in neuropsychiatric disorders and cancer progression." (PMID 34035217, 2021). "FoxQ1 protein levels were upregulated in 5 of 6 malignant tumor samples, whereas NRXN3 protein levels were downregulated in the 5 malignant tumor samples." (PMID 23383267, 2013). "However, no data regarding cellular and biological functions of human NRXN3, especially in cancer cells, are available." (PMID 23383267, 2013). "NLGN3 and NRXN3 were primarily expressed in cytosolic compartments rather than in the membrane, suggesting that their roles in cancer cells might be different from those in neurons." (PMID 37443071, 2023).
psychiatric disorder (6 papers, 2013 to 2025). A disorder characterized by behavioral and/or psychological abnormalities, often accompanied by physical symptoms. "Our data suggest that SNAP-25, NRXN3 and NRGN versus beta-amyloid and phosphorylated tau protein 181 (ptau) are regulated differentially across psychiatric disorders and that SNAP-25 has a moderate diagnostic potential for MDD and SCZ." (PMID 40840974, 2025). "NRXN3 [1242–1254] was significantly downregulated in the CSF of all studied psychiatric disorder groups (MDD: p < 0.01, BI: p < 0.01, SCZ: p < 0.05) in comparison to the control group." (PMID 32398672, 2020). "In addition, in line with the discovery and targeted proteomic findings, a downregulation of NRXN3 levels in the CSF of psychiatric disorders in comparison to the controls was detected using western blot." (PMID 32398672, 2020). "It reveals a biosignature of decreased synaptic protein levels including NRXN3 and CNTNAP4 in the CSF of psychiatric disorders, mainly MDD." (PMID 32398672, 2020). "We identified shared changes in CSF levels of some proteins across two or three major psychiatric disorders including MDD, BI disorder, and SCZ (e.g., NRXN3, CNDP1, LINGO1) indicating shared neuropathology across these diseases." (PMID 32398672, 2020). "Our study presents the first report on significantly decreased levels of NRXN3 and CNTNAP4 in the CSF of major psychiatric disorders, mainly MDD." (PMID 32398672, 2020).
neurodevelopmental disorder (5 papers, 2017 to 2025). A behavioral and cognitive disorder with onset during the developmental period that involves impaired or aberrant development of intellectual, motor, or social functions. "Neuronal populations showed enriched expression of neurodevelopmental disorder-linked genes (NRXN3, CADM2, ZNF536) and synaptic signalling pathways." (PMID 41010342, 2025). "Finally, it is worth noting that NRXN3 shows the lowest levels and the most restricted pattern of expression, and also the weakest association of gene polymorphisms with neurodevelopmental disorders (see Introduction section)." (PMID 28013231, 2017).
neurodegenerative disease (2 papers, 2023 to 2024). A disorder of the central nervous system characterized by gradual and progressive loss of neural tissue and neurologic function. "Two of them—Nrxn3 and Ldb2—are hubs in the transcriptional module related to neurodegenerative diseases, i.e., Nrxn3 in P60 and P120, and Ldb2 in P120." (PMID 37355705, 2023).
NRXN3 also shares sentences with these, for which no sentence is quoted: cognitive decline (2 papers); depression (2); epilepsy (2); Intellectual disability (2); neurological disease (2); adenocarcinoma (1); alcoholism (1); asthma (1); attention deficit-hyperactivity disorder (1); autoimmune encephalitis (1); Autoimmunity (1); Behcet disease (1); brain tumor (1); carbon monoxide poisoning (1); cardiovascular disease (1); celiac disease (1); central nervous system disorder (1); chronic lymphocytic leukemia (1); colorectal adenoma (1); colorectal carcinoma (1); diabetes (1); Glucose intolerance (1); Headache (1); hematological cancers (1); Hodgkins lymphoma (1); intrahepatic cholangiocarcinoma (1); language disorder (1); lung carcinoma (1); movement disorder (1); multiple myeloma (1).
A further 8 diseases each share a sentence with NRXN3 in 1 paper.